TTF1 (transcription termination factor 1)
Description:
Multifunctional nucleolar protein that terminates ribosomal gene transcription, mediates replication fork arrest and regulates RNA polymerase I transcription on chromatin. Plays a dual role in rDNA regulation, being involved in both activation and silencing of rDNA transcription. Interaction with BAZ2A/TIP5 recovers DNA-binding activity.
Synonyms: TTF-1; TTF-I
Tractability: PROTAC: UniProt records ubiquitination sites on it; ubiquitination databases record sites on it; its protein half-life has been measured.
Gene: Protein-coding gene on chromosome 9 (132,375,548 to 132,406,851, reverse strand). Ensembl gene ENSG00000125482.
Subcellular location: Nucleus; Nucleus, nucleolus; Nucleus, nucleoplasm
Subcellular location (Human Protein Atlas): Nucleoli fibrillar center
Pathways (Reactome):
Gene expression (Transcription): ERCC6 (CSB) and EHMT2 (G9a) positively regulate rRNA expression; NoRC negatively regulates rRNA expression; RNA Polymerase I Transcription Initiation; RNA Polymerase I Transcription Termination
Metabolism of proteins: Surfactant metabolism
Gene Ontology:
Molecular function: protein binding; chromatin binding
Biological process: DNA-templated transcription termination; termination of RNA polymerase I transcription
Cellular component: fibrillar center; nucleolus; nucleoplasm; nucleus
Genetic constraint (gnomAD): Loss-of-function variants: 60 observed, 73.05 expected, observed/expected ratio (o/e) 0.82, 90% interval 0.67 to 1.02. The upper end of that interval is the gene's LOEUF score, 1.02, which puts it in group 4 of 6, group 1 being the genes least tolerant of losing a copy. Missense variants: 968 observed, 1,066.3 expected, observed/expected ratio (o/e) 0.91, 90% interval 0.86 to 0.96. Synonymous variants: 357 observed, 377 expected, observed/expected ratio (o/e) 0.95, 90% interval 0.87 to 1.03.
Homologues: Orthologues: chimpanzee TTF1 (99% identical), macaque TTF1 (89% identical), dog TTF1 (60% identical), pig TTF1 (53% identical), rat Ttf1 (50% identical), mouse Ttf1 (50% identical), tropical clawed frog ttf1 (22% identical), zebrafish ttf1.3 (19% identical), zebrafish ttf1.2 (18% identical), zebrafish ttf1.6 (18% identical), zebrafish ttf1.1 (18% identical), zebrafish ttf1.5 (18% identical), and 1 more. Paralogues in human: SNAPC4 (10% identical), MYB (7% identical), MYBL1 (7% identical), MYBL2 (7% identical), DMTF1 (6% identical), CDC5L (5% identical).
Diseases named in the same sentence as TTF1 in open-access papers:
TTF1 is named in the same sentence as 261 diseases in open-access papers, as found by Europe PMC text mining. Sharing a sentence is not in itself a finding about the gene and the disease. The quoted sentences say what the papers report.
lung adenocarcinoma (284 papers, 2003 to 2026). A carcinoma that arises from the lung and is characterized by the presence of malignant glandular epithelial cells. "Awareness of TTF-1/Napsin A expression in rare extrapulmonary cancers, and their occasional absence in lung adenocarcinomas, is essential to avoid diagnostic errors." (PMID 40564811, 2025). "Given the high frequency of primary lung carcinomas and metastases, both from extrapulmonary primaries in the lung and from lung adenocarcinomas in other organs, TTF-1 is a widely used marker with diagnostic (and, consequently, clinical) importance." (PMID 40564811, 2025). "The presence of TTF-1 positivity, a marker commonly associated with lung adenocarcinoma, supports the diagnosis of metastatic lung adenocarcinoma to the prostate." (PMID 40740944, 2025). "IHC studies have shown TTF-1 positivity in 60–90% of lung adenocarcinoma cases and 82% of SCLC cases, making it a key diagnostic and prognostic tool." (PMID 39941799, 2025). "In 2011, the International Association for the Study of Lung Cancer, American Thoracic Society and European Respiratory Society introduced papillary subtype of lung adenocarcinoma coexisting with very high TTF-1 expression (90–100%) and 5% BRAF mutation." (PMID 39767631, 2024). "Thereby TTF‐1, assessed by immunohistochemistry (IHC), is considered a specific diagnostic biomarker for lung adenocarcinoma." (PMID 37775725, 2024). "Clinically, TTF-1 expression is a diagnostic tool for identifying the histological type of lung cancer, distinguishing primary lung adenocarcinomas from metastatic forms, and acting as a prognostic indicator." (PMID 39392394, 2024). "Further staining was performed using antibodies against thyroid transcription factor (TTF-1), which is highly expressed in lung adenocarcinoma and used as a diagnostic marker for lung cancer." (PMID 38360830, 2024). "TTF-1 is a regulator of surfactant protein expression, which is mainly expressed in lung adenocarcinoma and considered as one of the major diagnostic markers for lung adenocarcinoma." (PMID 35642043, 2022). "Correlative analyses were performed between the EML4-ALK mutation, the IGFR1, TTF1, and NapsinA expression, and the clinicopathologic factors in lung adenocarcinomas." (PMID 32876329, 2021). "TTF1 is most commonly used in diagnostic pathology as a marker of lung adenocarcinoma and thyroid tumors." (PMID 32245475, 2020). "We explored the prognostic impact of TTF-1 expression according to EGFR-sensitizing mutation status in lung adenocarcinoma patients." (PMID 31196060, 2019). "In contrast, the results of both previous studies and the present study indicate that TTF-1 was associated with prolonged survival in patients with lung adenocarcinoma." (PMID 31196060, 2019). "Thyroid transcription factor (TTF)-1 expression is a diagnostic marker and a good prognostic indicator for lung adenocarcinoma." (PMID 31196060, 2019). "TTF-1 is a lineage marker and has been used as a diagnostic marker for lung adenocarcinoma and small cell carcinoma." (PMID 31196060, 2019). "A left hilar lung adenocarcinoma (TTF1+) harbouring KRAS, PI3KCa and PTEN mutations was diagnosed, with left adrenal gland and cerebral metastasis." (PMID 31627742, 2019). "Pathologically, EGFR-mutated lung adenocarcinoma typically shows nuclear TTF-1 immunoreactivity and hobnail cell morphology." (PMID 29538329, 2018). "In this study, TTF-1 expression was also associated with EGFR expression in lung adenocarcinoma cell lines." (PMID 29079814, 2017). "The expression of TTF-1 was associated with tumor differentiation in resected lung adenocarcinoma patients (p < 0.001)." (PMID 29079814, 2017). "Expression of oncogenes including phospho-Src, phospho-β-catenin, c-myc, and cyclin D1 were also detected in the tumor-like tissues, as were diagnostic markers for lung adenocarcinoma, such as TTF1, NAPSA, CK7, and CK-HMW." (PMID 26871601, 2016).
lung adenocarcinoma (continued). "Because of its specific expression in lung adenocarcinomas, TTF-1 has been used as a diagnostic marker for primary and metastatic lung adenocarcinoma." (PMID 26705222, 2015). "In the NEJ 002 clinical study, we found that in patients with lung adenocarcinomas positive for thyroid transcription factor-1(TTF-1) expression, the EGFR mutation rate was higher." (PMID 24743427, 2014). "Several studies demonstrated an independent lower risk of death for lung adenocarcinoma patients whose tumor expresses positive TTF1 staining." (PMID 23706092, 2013). "The thyroid transcription factor 1 (TTF-1) gene is associated with the differentiation of lung epithelial cells and has been reported to be an independent prognostic factor for lung adenocarcinoma patients." (PMID 22940844, 2012). "Strong TTF-1 immunohistochemical expression is statistically associated with well-differentiated phenotype and inverse correlation with Ki-67 in Xuanwei lung adenocarcinomas." (PMID 22940844, 2012). "TTF1 has been described as a potential prognostic marker associated with improved survival for patients with stage I adenocarcinoma of the lung." (PMID 19563666, 2009). "Furthermore, thorough investigation of the thyroid transcription factor 1 (TTF1) gene revealed its crucial role in lung adenocarcinoma as either a diagnostic agent or a target for treatment." (PMID 40102990, 2025). "TTF1 and NapsinA are mainly used as diagnostic markers of lung adenocarcinomas in daily practice." (PMID 32876329, 2021). "This might explain why TTF-1 positivity has a more significant prognostic impact than the EGFR mutation status among patients with advanced lung adenocarcinoma in the EGFR-TKI era." (PMID 31196060, 2019). "Interestingly, the observation that TTF1 low expressing SCLC are more sensitive to inhibitors of DNA repair mirrors our previous findings in lung adenocarcinoma, suggesting a common effect of TTF1 loss in SCLC and LUAD in regards to DNA damage response." (PMID 29088717, 2017). "The TTF-1 positivity may be associated with the ERβ expression in lung adenocarcinoma with clinical significance, which therefore deserves further study." (PMID 28783064, 2017). "Based on this data, we hypothesize that TTF-1 expression in lung adenocarcinoma patients is correlated with EGFR mutations." (PMID 24743427, 2014). "Although the TTF1 gene is amplified in some lung adenocarcinoma cells and may function as an oncogene, loss of TTF-1 expression is reportedly associated with poor prognosis of lung carcinoma." (PMID 22111550, 2012). "With that being said, primary lung adenocarcinomas are also positive for TTF-1, which creates diagnostic confusion (if thyroglobulin is negative), when a poorly differentiated or anaplastic thyroid carcinoma is being differentiated from a primary lung adenocarcinoma." (PMID 27774331, 2016). "In summary, this study provides evidence that TTF-1 may reprogram lung cancer secreted proteome into an antiangiogenic state, offering a novel basis to account for the long-standing observation of favorable prognosis associated with TTF-1+ lung adenocarcinomas." (PMID 26912193, 2016). "K7 and TTF‐1 are the most sensitive and specific markers for identifying lung adenocarcinoma, while CDX2 and SATB2 are the most sensitive and specific markers for identifying colon cancer." (PMID 40309045, 2026). "To verify the histological origin of EP cell lines as lung adenocarcinoma, we evaluated the expression of adenocarcinoma markers Ttf1 and Napsa, as well as squamous cell carcinoma markers Krt5 and Np60 by qPCR." (PMID 41356800, 2026). "TTF‐1 immunohistochemical staining is useful for differentiating primary lung adenocarcinoma from another adenocarcinoma." (PMID 40309045, 2026). "We previously reported that thyroid transcription factor-1 (TTF-1) expression levels and tumor cell proportion are useful predictors of immunochemotherapy for lung adenocarcinoma." (PMID 42266151, 2026).
lung adenocarcinoma (continued). "Immunohistochemical analysis indicated negativity for lung adenocarcinoma markers TTF‐1 and squamous cell carcinoma markers p40, with retained INI‐1 expression." (PMID 41577374, 2026). "TTF‐1 identifies proliferating lesions in lung adenocarcinoma progression and differentiates them from squamous cell carcinoma lesions." (PMID 40650429, 2025). "Typical lung adenocarcinoma presents histologically as a gland‐forming tumor with neoplastic cells often immunoreactive for TTF‐1." (PMID 40028792, 2025). "In detail, at the time of the diagnosis, a TTF1‐positive lung adenocarcinoma was detected in a bronchial biopsy tissue, harboring KRASp.G12C mutations and PD‐L1 >50%." (PMID 40445863, 2025). "This group is characterized by the expression of lung lineage markers such as TTF-1 and Napsin A, which are highly sensitive and specific for lung adenocarcinoma." (PMID 41333480, 2025). "Thyroid transcription factor 1, TTF-1, is a nuclear marker that is highly specific for primary lung adenocarcinoma and is thus helpful in distinguishing pulmonary from extrapulmonary metastases." (PMID 41542005, 2025). "Resultant tumors and metastasis were validated using clinical markers of lung adenocarcinoma; TTF-1 and Napsin A and are PD-L1 positive." (PMID 40021683, 2025). "Immunohistochemical staining of the lumbar spine biopsy revealed positive results for TTF-1 and Napsin A, which are highly specific markers for lung adenocarcinoma." (PMID 40740944, 2025). "Lung cancer markers CK7 (+), TTF-1 (+), and NapsinA (+) are typical lung adenocarcinoma phenotypes, while P40 (-) and CK5/6 (-) can exclude squamous cell carcinoma." (PMID 40837582, 2025). "Background/Objectives: TTF-1 and Napsin A are immunohistochemical markers that are widely used for the diagnosis of lung adenocarcinomas or thyroid carcinomas, as well as the characterization of metastases." (PMID 40564811, 2025). "CK20 and CDX2 positivity, combined with TTF‐1 negativity, strongly suggest intestinal differentiation in primary lung adenocarcinomas." (PMID 39980580, 2025). "Thyroid Transcription Factor-1 (TTF-1) expression in lung adenocarcinoma (LUAD) has been studied for its prognostic value in early-stage and metastatic disease." (PMID 39630375, 2025). "Molecular diagnostics frequently employ biomarkers such as calretinin, CK5/6, WT‐1, mesothelin (MSLN), and D2‐40, whereas lung adenocarcinoma biomarkers typically include TTF‐1, napsin A, CEA, BerEP4, and claudin‐4." (PMID 40904706, 2025). "Histologically, resected lung nodules showed metastatic adenocarcinoma consistent with colorectal origin, yet the tumor cells paradoxically expressed thyroid transcription factor-1 (TTF-1) – a marker typically specific to primary lung adenocarcinoma." (PMID 41310725, 2025). "Although none of these animals became sick during this time, further histopathological analyses revealed the presence of lung adenocarcinomas positive for TTF-1 and SPC in 10 out of 22 PCic mice." (PMID 41219537, 2025). "This is in line with previous data linking TTF-1 positivity to a more favorable prognosis, probably resulting from TTF-1’s role in maintaining the differentiated state of lung adenocarcinoma cells, suggesting a less aggressive tumor phenotype." (PMID 39630375, 2025). "A 65-year-old man presented with cough and dyspnea and was diagnosed with stage IV EGFR exon 19 deletion well-differentiated lung adenocarcinoma (TTF-1+/CK7+), with metastases involving the right pleura, bilateral lungs, mediastinal lymph nodes, and bones." (PMID 41256964, 2025). "The lung adenocarcinomas are positive for TTF1 and Napsin A. We usually use TTF1 marker to confirm the diagnoses." (PMID 40407482, 2025). "Immunohistochemical analysis is therefore critical to distinguish metastatic breast carcinoma from lung adenocarcinoma; markers such as ER, PR, and GATA3 support a breast origin, whereas TTF-1 and napsin A favor lung adenocarcinoma." (PMID 41426883, 2025).
lung adenocarcinoma (continued). "Anti-TTF-1 antibodies are commonly used in routine pathology diagnostics, assisting in the differential diagnosis between squamous cell carcinomas and adenocarcinomas of the lung (which usually show TTF-1 positivity)." (PMID 40564811, 2025). "TTF-1 IHC and Napsin-A IHC are widely used by pathologists for confirmation of the diagnosis of lung adenocarcinoma, as well as thyroid carcinoma or their metastases and for distinction from other malignant entities." (PMID 40564811, 2025). "Before the 2015 update to the World Health Organization (WHO) classification, lung adenocarcinoma was diagnosed based on acinar or tubular patterns, mucin production, and the expression of TTF-1 and Napsin A." (PMID 39823974, 2025). "Immunohistochemistry (IHC) is central to resolving this dilemma: CRC typically shows CK7 negativity with CK20, CDX2, and SATB2 positivity, whereas primary lung adenocarcinomas are usually TTF-1 and CK7 positive, with Napsin A expression." (PMID 41310725, 2025). "HNF4α-positive cases among 241 lung adenocarcinomas were stratified based on TTF-1 and SMARCA4 expressions, histological subtypes, and driver mutations." (PMID 38710944, 2025). "In analogy to TTF-1, Napsin A expression is found not only in adenocarcinomas of the lung, but also in other entities." (PMID 40564811, 2025). "Pathological examination of the left eye mass confirmed that it shared the same histological origin as the lung cancer (TTF-1 positive, lung adenocarcinoma)." (PMID 41140667, 2025). "Among the tested markers, TTF-1 demonstrated high sensitivity and specificity for primary lung adenocarcinomas, while p40 was more specific than p63 for identifying squamous differentiation." (PMID 40746930, 2025). "For cancers that are CK20 negative and CK7 positive, the presence of p63 often suggests lung squamous carcinoma, while the presence of TTF1 largely indicates lung adenocarcinoma." (PMID 40242159, 2025). "In this case, TTF-1 and CK7 positivity is characteristic of lung adenocarcinoma and less likely to be associated with primary breast cancer." (PMID 39958078, 2025). "On the other hand, this report sheds light on the underdiagnosis of TC, which is misdiagnosed as TTF-1+ lung adenocarcinoma." (PMID 39767631, 2024). "In adenocarcinomas, TTF-1 has been shown to play a significant role in the pathogenesis of lung cancer, being expressed in 69–80% of lung adenocarcinoma cases." (PMID 39392394, 2024). "Studies have shown that patients with positive TTF-1 expression exhibit longer overall survival (OS) in stage I lung adenocarcinoma." (PMID 39392394, 2024). "IHC staining for the lung adenocarcinoma–specific marker TTF-1 demonstrated strong nuclear expression, further confirming the presence of a primary pulmonary adenocarcinoma." (PMID 39718828, 2024). "CMT167 cells are TTF-1 positive and exhibit histology consistent with lung adenocarcinoma but appear more representative of the papillary sub-type rather than solid subtype." (PMID 38994972, 2024). "Thyroid transcription factor‐1 (TTF‐1) assessed by immunohistochemistry (IHC) is a specific biomarker for lung adenocarcinoma, and is commonly used to confirm the pulmonary origin of neuroendocrine tumours (NET)." (PMID 37775725, 2024). "Despite a large meta-analysis linking TTF-1 overexpression in human lung adenocarcinoma with improved survival, the data is largely conflicting." (PMID 38994972, 2024). "According to available evidences, TTF-1 positivity is considered an established positive prognostic factor for lung adenocarcinomas." (PMID 37775725, 2024). "In the high specialization era (according to this classification), our patients (especially the second one) were misdiagnosed with lung adenocarcinoma, since TTF-1 seemed to be the single best marker." (PMID 39767631, 2024).